GRPR (gastrin releasing peptide receptor)
Diseases named in the same sentence as GRPR in open-access papers (continued):
Sharing a sentence is not in itself a finding about the gene and the disease.
cancer (continued). "PD176252 (GRPR antagonist) and SR48692 (NTSR1 antagonist) inhibit cancer growth." (PMID 30008698, 2018). "Only a minority of the never smoker and former smoker surgical cancer-free control subjects had GRPR bronchial expression while, the majority of actively smoking surgical controls had detectable GRPR bronchial expression." (PMID 22296774, 2012). "Peptides generated by linking the gastrin-releasing peptide receptor (GRPR)-selective ligand to multiple bis-deoxygalactosyl-carborane building blocks showed selectivity for PC3 cancer cells but not for HepG2 cells, suggesting a reduced uptake into liver cells." (PMID 39768156, 2024). "The binding of antagonists to GRPR does not trigger the activation of the receptor nor the following cascade response leading to the insurgence of side effects and has even demonstrated antiproliferative effects on several cancer models." (PMID 38020178, 2023). "However, monitoring differential expression of GRPR in different types of cancers using non-invasive and non-radioactive MR molecular imaging has not yet to be achieved." (PMID 26577829, 2015). "There is also ongoing research developing gastrin-releasing peptide receptor (GRPR) antagonists, given its expression in early-stage hormone-sensitive cancers, unlike PSMA, which is more present in late-stage cancer." (PMID 40868092, 2025). "Furthermore, 99mTc-3P4-RGD2 can only detect GRPR-positive cancer, while 99mTc-RGD-BBN can successfully detect tumors when integrin αvβ3 or GRPR is not expressed at the same time." (PMID 34771622, 2021).
psychiatric disorder (5 papers, 2007 to 2021). A disorder characterized by behavioral and/or psychological abnormalities, often accompanied by physical symptoms. "Together, these findings constitute a consistent body of evidence supporting the viewthat drugs acting at the GRPR should be further evaluated as potential cognitiveenhancers to treat memory disorders associated with AD and other neurodegenerativeand psychiatric disorders." (PMID 29213377, 2007). "Alterations in GRP or GRPR expression or function have been reported in patients with neurodegenerative, neurodevelopmental, and psychiatric disorders." (PMID 34301297, 2021). "Based on these findings, we have put forward that the GRPR may be a novel molecular target for the development of therapeutic strategies for patients with neurological and psychiatric disorders." (PMID 23251133, 2012). "Increasing evidence indicates that bombesin (BB)-like peptides (BLPs), such asthe gastrin-releasing peptide (GRP) and its receptor (GRPR), might play a rolein neurological and psychiatric disorders." (PMID 29213377, 2007).
bacterial infections (1 paper, 2021). "Industry has put in efforts to establish licensed cold kits (e.g. SomaKit TOC, NETSPOT), while other cold kits addressing targets like PSMA, gastrin releasing peptide receptors (GRPR), integrin receptors or bacterial infections are available without marketing authorization." (PMID 34495412, 2021).
CNS tumors (1 paper, 2025). "These agents target distinct molecular markers, such as gastrin-releasing peptide receptor (GRPR), translocator protein (TSPO), and integrin-αvβ3, that have been shown to be overexpressed in various CNS tumors." (PMID 40563556, 2025). "Collectively, these emerging tracers targeting GRPR, TSPO, and integrin-αvβ3 demonstrate feasibility for receptor-based imaging in pediatric CNS tumors." (PMID 40563556, 2025).
head and neck neoplasm (1 paper, 2025). A benign or malignant neoplasm that affects the anatomic structures of the head and neck region. "The focus of this study was to assess GRPR expression in head and neck tumors, which most commonly originate in the squamous cells lining the mucosal surfaces of these sites." (PMID 41266536, 2025).
neurodevelopmental disorder (1 paper, 2012). A behavioral and cognitive disorder with onset during the developmental period that involves impaired or aberrant development of intellectual, motor, or social functions. "Although a causative role of GRPR dysfunction in CNS disorders has not been directly established, some alterations in the levels of BLPs peptides or GRPR density or function have been observed in patients with psychiatric, neurodegenerative, and neurodevelopmental disorders." (PMID 23251133, 2012).
GRPR also shares sentences with these, for which no sentence is quoted: adenocarcinoma (4 papers); Breast (3); brain cancer (2); gastrinomas (2); infection (2); leukemia (2); lung adenocarcinoma (2); Arthritis (1); brain disorder (1); cervical dysplasia (1); cervical tumors (1); cholestasis (1); colorectal adenocarcinoma (1); colorectal tumors (1); diabetes mellitus (1); Ehrlich tumor (1); epilepsy (1); hepatocellular carcinoma (1); hypothyroidism (1); invasive lobular carcinoma (1); leiomyoma (1); lymphoma (1); malignant glioma (1); medullary carcinoma of the thyroid (1); neurological diseases (1); oral squamous cell carcinoma (1); pancreatitis (1); post-traumatic stress disorder (1); pulmonary obstruction (1); severe combined immunodeficiency (1).
A further 3 diseases each share a sentence with GRPR in 1 paper.